NDNF (neuron derived neurotrophic factor)
Description:
Secretory protein that plays a role in various cellular processes. Acts as a chemorepellent acting on gonadotropin-releasing hormone (GnRH) expressing neurons regulating their migration to the hypothalamus. Also promotes neuron migration, growth and survival as well as neurite outgrowth and is involved in the development of the olfactory system. May also act through the regulation of growth factors activity and downstream signaling. Also regulates extracellular matrix assembly and cell adhesiveness (By similarity). Promotes endothelial cell survival, vessel formation and plays an important role in the process of revascularization through NOS3-dependent mechanisms.
Synonyms: C4orf31; FLJ23191; HH25; NORD
Tractability: Antibody: UniProt places it where antibodies can reach, with high confidence; its Gene Ontology location is reachable by antibodies, with high confidence; UniProt predicts a signal peptide or a membrane-spanning region. PROTAC: its protein half-life has been measured.
Gene: Protein-coding gene on chromosome 4 (121,033,326 to 121,074,085, reverse strand). Ensembl gene ENSG00000173376.
Subcellular location: Secreted
Subcellular location (Human Protein Atlas): Vesicles; Predicted to be secreted
Gene Ontology:
Molecular function: glycosaminoglycan binding; heparin binding
Biological process: angiogenesis; cellular response to fibroblast growth factor stimulus; negative regulation of neuron apoptotic process; neuron migration; positive regulation of neuron projection development; signal transduction; extracellular matrix organization; gonadotrophin-releasing hormone neuronal migration to the hypothalamus; positive regulation of cell-substrate adhesion; vascular wound healing; response to ischemia
Cellular component: extracellular region; extracellular matrix; non-collagenous component of interstitial matrix
Genetic constraint (gnomAD): Loss-of-function variants: 14 observed, 39.33 expected, observed/expected ratio (o/e) 0.36, 90% interval 0.23 to 0.56. The upper end of that interval is the gene's LOEUF score, 0.56, which puts it in group 2 of 6, group 1 being the genes least tolerant of losing a copy. Missense variants: 577 observed, 650.31 expected, observed/expected ratio (o/e) 0.89, 90% interval 0.83 to 0.95. Synonymous variants: 229 observed, 247.1 expected, observed/expected ratio (o/e) 0.93, 90% interval 0.83 to 1.03.
Homologues: Orthologues: chimpanzee NDNF (99% identical), macaque NDNF (98% identical), pig NDNF (96% identical), dog NDNF (95% identical), guinea pig NDNF (94% identical), rabbit NDNF (92% identical), mouse Ndnf (88% identical), rat Ndnf (87% identical), tropical clawed frog ndnf (85% identical), zebrafish ndnf (78% identical), Caenorhabditis elegans ndnf-1 (19% identical), Drosophila melanogaster nord (18% identical).
Diseases named in the same sentence as NDNF in open-access papers:
NDNF is named in the same sentence as 34 diseases in open-access papers, as found by Europe PMC text mining. Sharing a sentence is not in itself a finding about the gene and the disease. The quoted sentences say what the papers report.
congenital hypogonadotropic hypogonadism (3 papers, 2021 to 2025). Congenital hypogonadotropic hypogonadism (CHH) is a rare disorder of sexual maturation characterized by gonadotropin (Gn) deficiency with low sex steroid levels associated with low levels of follicle stimulating hormone (FSH) and luteinizing hormone (LH). "Although NDNF was recently reported as a novel causative gene for congenital hypogonadotropic hypogonadism (CHH), this conclusion has yet to be validated." (PMID 33531459, 2021). "Remarkably, NDNF mutants were discovered in the genomes of several probands with congenital hypogonadotropic hypogonadism (CHH), a rare genetic disorder that is characterized by absence of puberty, infertility, and anosmia (loss of smell)." (PMID 35037619, 2022). "Nord is related to the vertebrate Neuron-Derived Neurotrophic Factor (NDNF) involved in congenital hypogonadotropic hypogonadism and several types of cancer." (PMID 35037619, 2022).
Anosmia (2 papers, 2022 to 2025). An inability to perceive odors. "Among the strongest genetic links, pathogenic variants in neuron-derived neurotrophic factor (NDNF) have been identified in patients with CHH and Kallmann syndrome." (PMID 41614834, 2025).
autism (2 papers, 2019 to 2026). Persistent deficits in social interaction and communication and interaction as well as a markedly restricted repertoire of activity and interest as well as repetitive patterns of behavior. "Other protein factors with altered expression in LPFC layer 1 in autism include chemokine ligand 14 (CXCL14) and neuron-derived neurotrophic factor (NDNF)." (PMID 30867066, 2019).
syphilis (2 papers, 2023 to 2025). A contagious bacterial infection caused by the spirochete Treponema pallidum. "In addition, neuron-derived neurotrophic factor (NDNF) was identified as a novel antigen in all five cases of syphilis-associated membranous nephropathy by mass spectrometry." (PMID 38129918, 2023). "In addition to IgG, neuron-derived neurotrophic factor (NDNF), a novel target antigen, has now been identified as a more specific marker for nephrotic syndrome caused by syphilis." (PMID 40585618, 2025). "While this case has limitations, including a lack of NDNF testing, limited follow-up, and single case generalizability, it demonstrates that nephrotic syndrome from syphilis is easily treatable." (PMID 40585618, 2025). "While this patient did not undergo testing for NDNF, it is important to consider it as it could be used in future cases as a confirmatory test for syphilis-induced MN in a patient who may have several other comorbidities." (PMID 40585618, 2025).
Autoimmunity (1 paper, 2025). The occurrence of an immune reaction against the organism's own cells or tissues. "The podocyte-focused expression of PLA2R1, NTNG1, HTRA1, and NDNF is intriguing, highlighting antigen-initiated autoimmunity as causing podocyte injury and the subsequent MN pathogenesis." (PMID 40149392, 2025).
heart failure (1 paper, 2019). Inability of the heart to pump blood at an adequate rate to meet tissue metabolic requirements. "Collectively, these data suggested that implantation of NDNF‐overexpressing old hADSCs promoted cardiac repair and delayed progressive heart failure possibly through restoration of NDNF level and improving angiogenesis." (PMID 31287219, 2019). "After in vivo implantation of NDNF‐overexpressing old hADSCs, angiogenesis was facilitated which improved collateral circulation in the infarcted area and eventually led to the preservation in cardiac function and delaying the progression of heart failure." (PMID 31287219, 2019).
infarction (1 paper, 2018). A localised pathological necrosis of tissue resulting from obstruction of the blood supply usually by a thrombus, an embolus, or vascular torsion. "Neuron-derived neurotrophic factor (NDNF), a proangiogenic secreted protein with a fibronectin type III domain, improves poor myocardial remodeling after infarction and enhances cardiac cell survival and angiogenesis through a focal adhesion kinase/Akt-dependent pathway." (PMID 29744364, 2018).
ischemia (1 paper, 2025). A hypoperfusion of the BLOOD through an organ or tissue caused by a PATHOLOGIC CONSTRICTION or obstruction of its BLOOD VESSELS, or an absence of BLOOD CIRCULATION. "Neuron-derived neurotrophic factor can also modulate endothelial cell function in ischemia-induced revascularization through the activation of Akt/endothelial NOS (eNOS) signaling." (PMID 39550735, 2025).
lung adenocarcinoma (1 paper, 2022). A carcinoma that arises from the lung and is characterized by the presence of malignant glandular epithelial cells. "Additionally, recent studies have shown that NDNF expression is significantly downregulated in human lung adenocarcinoma (LUAD) and renal cell carcinoma (RCC), indicating that NDNF may also provide a beneficial function as a tumor suppressor." (PMID 35037619, 2022).
male infertility (1 paper, 2023). The inability of the male to effect fertilization of an ovum after a specified period of unprotected intercourse. "According to the literature, there has been limited evidence for the association of AKAP4, CCIN and NDNF genes with male infertility." (PMID 37670815, 2023). "Intersection of genes from transcriptomic studies with genes with identified rare variants revealed a total of 7 genes linked with male infertility phenotype (CYP11A1, CYP17A1, RSPH3, TSGA10, AKAP4, CCIN, NDNF)." (PMID 37670815, 2023).
myocardial infarction (1 paper, 2019). Gross necrosis of the myocardium, as a result of interruption of the blood supply to the area, as in coronary thrombosis. "The effects of transplantation of NDNF over‐expression stem cells on heart repair after myocardial infarction (MI) in adult mice were investigated." (PMID 31287219, 2019).
Parkinson disease (1 paper, 2019). A progressive degenerative disorder of the central nervous system characterized by loss of dopamine producing neurons in the substantia nigra and the presence of Lewy bodies in the substantia nigra and locus coeruleus. "We also find that a heme-containing neurotrophic factor, neuron-derived neurotrophic factor [NENF], couples with Parkinson disease-related proteins to promote neurotrophic activity." (PMID 31536960, 2019).
renal carcinoma (1 paper, 2022). A carcinoma arising from the epithelium of the renal parenchyma or the renal pelvis. "The neuron-derived neurotrophic factor (NDNF) is a glycosylated, disulfide-bonded secretory protein that contains a fibronectin type III domain and suppresses the EMT in RCC cells to inhibit migration and invasion of renal cancer cells." (PMID 36092962, 2022).
cancer (3 papers, 2021 to 2022). A tumor composed of atypical neoplastic, often pleomorphic cells that invade other tissues. "As opposed to the majority of the selected targets, that have established oncogenic roles, NDNF and OR4D6, to the best of our knowledge, have no previously known association with cancer progression or drug resistance." (PMID 33767353, 2021).
NDNF also shares sentences with these, for which no sentence is quoted: genetic diseases (2 papers); infection (2); tumor (2); abscess (1); acute stress disorder (1); alcohol dependence (1); Alzheimer disease (1); autism spectrum disorder (1); cyst (1); hypogonadotropic hypogonadism (1); immune complex disease (1); Infertility (1); membranous nephropathy (1); nephrotic syndrome (1); neurodevelopmental disorder (1); neuronal migration disorders (1); Noonan syndrome (1); plasma cell disorders (1); renal cell carcinoma (1); skin disorder (1).